LEP (leptin)
Diseases named in the same sentence as LEP in open-access papers (continued):
Sharing a sentence is not in itself a finding about the gene and the disease.
melanoma (continued). "A recent study in a mouse melanoma model demonstrated that the frequency of CD8+ T cells expressing exhaustion markers (PD-1, TIM3 and LAG3) were significantly higher both at the tumor site and systemically in obese mice compared to their lean counterparts implicating leptin as the mediator." (PMID 32549336, 2020). "The authors suggested that leptin is not essential for melanoma growth but may accelerate tumor growth." (PMID 24202338, 2013). "Leptin treatment following the subcutaneous injection of melanoma cells into C57BL/6 mice resulted in larger tumor size, higher capillary density and increased plasma levels of VEGF, supporting that, as an angiogenic and mitogenic factor, leptin could promote melanoma growth." (PMID 33260746, 2020). "The absence of effects on weight and food intake suggested that the central actions of leptin were not disrupted by low-dose 2.17-mAlb although the low-dose nanobody administered adjacent to the tumor was sufficient to decrease the growth of a highly aggressive melanoma by 33%." (PMID 24587106, 2014). "The amount of VEGF in tissue was higher in the melanomas from obese mice and independent of neither circulating VEGF level nor host plasma leptin." (PMID 34068679, 2021). "Firstly, to explore whether leptin and resistin could have any role in modulating the sensitivity of melanoma cells to DTIC, A375 cells were treated with DTIC in the presence or absence of leptin or resistin." (PMID 29568521, 2018).
schizophrenia (47 papers, 2011 to 2026). A major psychotic disorder characterized by abnormalities in the perception or expression of reality. "As several researches provided more information on the impact of antipsychotics on leptin levels than the association between schizophrenia and leptin." (PMID 35197874, 2022). "Regression analysis suggested that only LEP-CpG7 methylation was negatively associated with positive symptoms in patients with schizophrenia." (PMID 35197874, 2022). "Previous literature in schizophrenia shown that leptin levels were positively associated with TC, TG and percentage of body fat and negatively related to HDL-C." (PMID 36090349, 2022). "In view of the limited power, the significant association of leptin methylation, mRNA expression and schizophrenia is noteworthy." (PMID 35197874, 2022). "The dysregulation of adipokine levels has been associated with schizophrenia and other related disorders, with Olanzapine, clozapine, and quetiapine shown to elevate the pro-inflammatory cytokine, leptin." (PMID 36151087, 2022). "LEP-CpG7 methylation was negatively associated with positive symptoms in patients with schizophrenia." (PMID 35197874, 2022). "The characteristics of SNPs and their genetic associations with circulating leptin/sOB-R levels and schizophrenia." (PMID 34777056, 2021). "Numerous studies have shown that Olz-induced weight gain is associated with elevated leptin levels in schizophrenia patients." (PMID 24349027, 2013). "Cannabinoid receptor 1 (CNR1) and leptin gene (LEP) may also be associated with weight gain in schizophrenia patients treated with first and second generation antipsychotics." (PMID 36983567, 2023). "Recently, the hypothesis of leptin dysregulation has been associated with psychopathology in schizophrenia." (PMID 35197874, 2022). "However, a recent finding shown that schizophrenia was still closely associated with increased leptin levels compared with the healthy when considering gender, age and BMI." (PMID 35197874, 2022). "LEP-CpG7 methylation may be negatively associated with positive symptoms in patients with schizophrenia." (PMID 35197874, 2022). "In addition, studies on patients without medication have shown that low leptin levels are associated with schizophrenia, and antipsychotics will increase leptin levels." (PMID 34566714, 2021). "Although there are suggestions that leptin may be a biomarker for the prognosis of schizophrenia, it remains unclear whether this hormone is associated with particular psychopathological parameters." (PMID 34566714, 2021). "In other studies of patients with schizophrenia, both adiponectin and leptin levels were found to be associated with most metabolic parameters, which may be due to the fact that the assessment did not take into account the presence of MetS." (PMID 33066473, 2020). "Another possible explanation is that secretion of estrogen or leptin from stored bodily fat might protect bone loss in female patients with schizophrenia, as these patients have more body fat than the general population." (PMID 22348381, 2012). "Furthermore, LEP-CpG7 methylation may be negatively associated with positive symptoms in patients with schizophrenia." (PMID 35197874, 2022). "A proteomic analysis found that insulin and leptin in the plasma of patients with MDD or schizophrenia increase, illustrating that MDD patients already have metabolic abnormalities before medical treatment." (PMID 40123458, 2025). "SNP rs3828942 of LEP and rs17047718 of INSIG2 have been implicated in MetS in patients with schizophrenia." (PMID 38540239, 2024). "The fourth week of a study involving 13 schizophrenia patients receiving OLZ showed an increase in serum leptin levels." (PMID 40259963, 2024). "Independent research has linked the genes that govern inflammation, glucose metabolism, leptin signaling, and fat mass to schizophrenia." (PMID 37425327, 2023).
schizophrenia (continued). "Previous studies have shown that patients with schizophrenia taking antipsychotics have higher leptin levels, particularly in those taking second-generation antipsychotics." (PMID 37091807, 2023). "A case-control study illustrated that lower leptin levels in peripheral blood was closely related to more severe positive symptoms of schizophrenia." (PMID 35197874, 2022). "The role of leptin in persons with schizophrenia is the extent of its interaction with dopaminergic regulation." (PMID 35806096, 2022). "To date, there is no relative report exploring the potential pathogenesis and psychopathology of schizophrenia regarding DNA methylation regulation and mRNA expression of leptin." (PMID 35197874, 2022). "As far as we know, this is the first study to investigate leptin CpG sites methylation in the promoter region and mRNA expression changes using the MassARRAY system and RT-PCR in patients with schizophrenia." (PMID 35197874, 2022). "In conclusion, this study indicated that there was leptin CpG site methylation in the promoter region and mRNA expression dysregulation in schizophrenia inpatients." (PMID 35197874, 2022). "Several studies demonstrated that increased leptin levels were heavily dependent on weight gain or BMI in patients with schizophrenia." (PMID 35197874, 2022). "Some inconsistencies are presented in literature regarding the differential link between clinical symptoms of schizophrenia and leptin in peripheral blood." (PMID 35197874, 2022). "Increased serum leptin concentrations have been found more frequently in patients with schizophrenia, especially when taking antipsychotics, which is consistent with our results." (PMID 36294794, 2022). "For example, dysregulations of insulin, cortisol, glucagon, glucagon-like peptide 1, cholecystokinin, adiponectin, ghrelin, leptin, orexin, prolactin, and oxytocin have been observed during treatment with antipsychotics among persons with schizophrenia." (PMID 35806096, 2022). "In the current study of people with schizophrenia, we found highly significantly higher leptin levels in the serum of 90 patients with MetS than in those 105 without MetS." (PMID 36294794, 2022). "During the treatment of schizophrenia, leptin levels and insulin levels were also positively correlated." (PMID 36090349, 2022). "Various works of literature have indicated that plasma leptin levels in schizophrenia patients were positively correlated with the HOMA-IR index and this relationship persisted after pharmacological treatment." (PMID 36090349, 2022). "There was significant up-regulated leptin mRNA expression in schizophrenia compared with HC subjects." (PMID 35197874, 2022). "A recent study in persons with schizophrenia revealed a drop in leptin levels after the initiation of antipsychotics for 6 weeks." (PMID 35806096, 2022). "Few studies have explored leptin changes in patients with psychopathologies, especially in Chinese patients with schizophrenia." (PMID 34566714, 2021). "If leptin can relieve psychopathological symptoms, then weight gain in patients with schizophrenia is of concern." (PMID 34566714, 2021). "Recently, attention has been focused on the effect of leptin on psychopathological symptoms in patients with schizophrenia." (PMID 34566714, 2021). "Our study aimed to elucidate the relationships between serum leptin levels, body mass index (BMI), and psychopathology symptoms in patients with schizophrenia." (PMID 34566714, 2021). "In summary, this study showed that serum leptin levels in patients with schizophrenia were negatively correlated with the three subscales of PANSS (PANSS-P, PANSS-N, PANSS-G), the total scale score, and the BPRS score." (PMID 34566714, 2021). "We measured in 46 patients with schizophrenia and MetS serum levels of adiponectin insulin, leptin, TNF-α and IL-6 and compared these levels to those of patients with schizophrenia without MetS." (PMID 33066473, 2020).
schizophrenia (continued). "Taken together, the CEBPA-induced alterations in leptin levels have potential roles in at least some aspects of pathobiology of schizophrenia." (PMID 33093650, 2020). "Our results support an important pathophysiological role for leptin more than adiponectin in patients with schizophrenia with MetS." (PMID 33066473, 2020). "Among adipocytokines, we found significant changes in the levels of leptin and adiponectin and their ratios in patients with schizophrenia with MetS." (PMID 33066473, 2020). "They found that adiposity-related elevations in plasma leptin concentrations in antipsychotic-treated patients with schizophrenia are highly comparable to those observed in untreated healthy control subjects." (PMID 32033608, 2020). "Elevated blood leptin levels are observed in patients with schizophrenia, particularly in those taking SGAs." (PMID 33551872, 2020). "They compared leptin levels between 72 schizophrenia patients chronically treated with olanzapine, risperidone or typical antipsychotics and 124 healthy adult control subjects." (PMID 32033608, 2020). "Leptin modulates activity of mesolimbic dopaminergic neurons in the hypothalamus, which is especially important in schizophrenia." (PMID 29163240, 2017). "Baseline plasma leptin can have an effect on subsequent weight gain following OLZ treatment in female patients with schizophrenia." (PMID 26930407, 2016). "Positive correlation between leptin level and PANSS suggested a potential role for leptin which can mediate the link between antipsychotic induced weight gain and therapeutic response in schizophrenia." (PMID 27610173, 2016). "In our previous papers, it has been demonstrated that polymorphisms in insulin-induced gene 2 (INSIG2), LEP, FTO, dopamine D2 receptor (DRD2), and 5-HT receptor genes may contribute to the development of metabolic disorders in schizophrenia." (PMID 38540239, 2024). "Researchers have identified specific genetic variations in the LEP and HTR2C genes that may be linked to psychopharmacological treatment and its influence on BMI in patients with schizophrenia." (PMID 37623307, 2023). "In addition, patients with schizophrenia exhibited significant lower LEP-mRNA expression (z = −2.203, P = 0.028) when compared with HC groups after using the Mann-Whitney U-test." (PMID 35197874, 2022). "We examined 195 patients with schizophrenia (90 with and 105 without MetS) for the association of serum levels of ghrelin, insulin, and leptin with metabolic abnormalities." (PMID 36294794, 2022). "Altogether, the recent evidence suggests that leptin, which induced potential hippocampal synaptic neuroplasticity, may be play a great role in the pathophysiology of schizophrenia." (PMID 35197874, 2022). "Therefore, we aimed to explore the regulation of DNA methylation of leptin promoters and mRNA expression in patients with schizophrenia." (PMID 35197874, 2022). "In addition, in a double-blind crossover study examining satiety signaling, a decrease in leptin was found after intranasal oxytocin administration in persons with schizophrenia." (PMID 35806096, 2022). "Here, we presume that schizophrenic patients may undergo abnormal DNA promoter methylation and mRNA expression of leptin, an important neurodevelopmental gene, and it probably plays an important role in pathogenesis of schizophrenia." (PMID 35197874, 2022). "In addition, plasma leptin levels in schizophrenia patients were negatively correlated with positive symptoms, negative symptoms, depressive factor scores, general psychopathology and PANSS total scores, which were generally consistent with the our findings." (PMID 36090349, 2022). "Our present finding of elevated leptin mRNA expression in patients with schizophrenia supports this speculation." (PMID 35197874, 2022). "The authors suggested that the modulation of leptin by oxytocin may have effects on not only the metabolic parameters but on the treatment of schizophrenia." (PMID 35806096, 2022).
schizophrenia (continued). "For the first time, we put forward a hypothesis of abnormal regulation of leptin methylation and mRNA expression in patients with schizophrenia." (PMID 35197874, 2022). "It is the first study to suggest that leptin may play a role in the relationship between antipsychotics-induced weight gain and favorable treatment response in schizophrenia." (PMID 34566714, 2021). "More studies have shown that the role of leptin in protecting cell survival, promoting apoptosis, and dopamine regulation may be the main mechanism for improving the psychopathological symptoms of schizophrenia." (PMID 34566714, 2021). "The role of leptin in the pathobiology of schizophrenia is obscure." (PMID 33093650, 2020). "Notably, studies of multiple-episode schizophrenia patients revealed increased levels of leptin and insulin." (PMID 32547431, 2020). "Indeed, two recent meta-analyses showed an increase in leptin for schizophrenia patients compared to controls, with more marked elevation during decompensations episodes." (PMID 32033608, 2020). "Remarkably, elevated leptin levels have also been observed in patients with schizophrenia." (PMID 33066473, 2020). "Indeed, there is evidence that multiple-episode schizophrenia patients present with increased leptin levels." (PMID 32547431, 2020). "Data Sources: MEDLINE, Google Scholar, Cochrane Database and PsycINFO databases were searched for articles containing all the following exploded MESH terms: schizophrenia [AND] antipsychotic agents/neuroleptics [AND] (weight gain [OR] lipids [OR] insulin [OR] leptin) [AND] treatment outcome." (PMID 29403343, 2017). "Furthermore, individuals with schizophrenia who are receiving treatment with first- and second-generation antipsychotics may gain weight due to genes like leptin (LEP) and cannabinoid receptor 1 (CNR1)." (PMID 40676294, 2025). "According to a systematic review, for FTO and leptin and leptin receptor genes (LEP and LEPR), for the methylenetetrahydrofolate reductase (MTHFR) gene, and for the serotonin receptor 2C gene (HTR2C), there is strong evidence of association with MetS in schizophrenia patients." (PMID 38540239, 2024). "Thus, plasma leptin levels in schizophrenia patients may play an important mediating role between antipsychotic-induced disorders of glucolipid metabolism and clinical symptom remission." (PMID 36090349, 2022). "Hence analyzing leptin CpG sites methylation and LEP-mRNA expression in peripheral blood are utile and profound means of exploring the mechanisms of action of leptin that underlie complex variation in mental and psychological features of schizophrenia." (PMID 35197874, 2022). "Partial correlations between LEP-CpG methylation, LEP-mRNA expression and PANSS scores in patients with schizophrenia, controlled for gender, age, BMI, dose of antipsychotic, and duration of illness (n = 40)." (PMID 35197874, 2022). "The results of our study show that the LEP and INSIG2 genes can play an important role in the development of MetS in patients with schizophrenia." (PMID 35627229, 2022). "However, previous studies noticed an elevation in serum leptin levels among persons with schizophrenia treated with antipsychotics, and the evidence suggested that the hyperleptinemic state could be more of a consequence than a cause of antipsychotic-induced weight gain." (PMID 35806096, 2022). "In agreement with our findings, schizophrenia patients treated with olanzapine exhibited higher serum leptin levels, while adiponectin levels did not change." (PMID 40969408, 2025). "In one of our previous studies, we found significantly increased leptin levels in schizophrenia patients with compared to those without MetS." (PMID 36294794, 2022). "Leptin correlates with BMI at an average level in schizophrenia patients without MetS and also has weak correlations with waist circumference, triglycerides, and VLDL." (PMID 36294794, 2022).
schizophrenia (continued). "As a result of our study, a statistically significant increase in leptin concentration (p < 0.001) and a decrease in ghrelin levels (p = 0.045) were observed in patients with schizophrenia with MetS compared to the group without MetS." (PMID 36294794, 2022). "In this study, we observed significantly higher LEP-CpG7, LEP-CpG15 methylation and lower LEP-CpG11, LEP-CpG33.34.35, LEP-CpG36 methylation in inpatients with schizophrenia, which were never reported in previous studies." (PMID 35197874, 2022). "Plasma leptin, HOMA-IR and hs-CRP levels should be measured regularly in CS patients to prevent or treat the disorders of glucose and lipid metabolism comorbidity with schizophrenia patients in clinical diagnosis and treatment." (PMID 36090349, 2022). "In our study, we showed that leptin levels and leptin–adiponectin ratios were significantly increased and adiponectin levels significantly decreased in patients with schizophrenia with MetS in comparison to patients without MetS." (PMID 33066473, 2020). "However, even partially independent of BMI and therapy, leptin is elevated in patients with schizophrenia compared to healthy subjects." (PMID 36294794, 2022). "We assumed that previous analysis might not control confounding variables, such as dose of antipsychotics, duration of illness etc., or that abnormal leptin expression might be not specific for depressive symptoms of schizophrenia." (PMID 35197874, 2022). "We found significant decreases in the serum concentrations of adiponectin (p = 0.002) and increases in the leptin serum levels (p < 0.001) and the leptin–adiponectin ratios (p = 0.002) in patients with schizophrenia with MetS in comparison to patients without MetS." (PMID 33066473, 2020). "However, only patients with schizophrenia but without MetS demonstrated a relationship between leptin and visceral fat levels." (PMID 33066473, 2020). "The raised leptin levels found in some studies among schizophrenia patients could be explained by the negative feedback against increased in brain dopamine activity associated with positive symptoms since leptin has been proved to modulate mesolimbic dopamine system." (PMID 32033608, 2020). "In this study, serum leptin was negatively correlated with positive, negative, general pathological symptoms and PANSS total BPRS score in patients with schizophrenia." (PMID 34566714, 2021).